S100P (S100 calcium binding protein P)
Diseases named in the same sentence as S100P in open-access papers (continued):
Sharing a sentence is not in itself a finding about the gene and the disease.
lung carcinoma (continued). "S100P was found to increase the migration and invasion of cancer cells in lung cancer." (PMID 38750571, 2024). "The S100P gene is found in a range of cancers such as pancreatic, breast, prostate and lung cancers and is linked to negative clinical results." (PMID 39602465, 2024). "Consistent with the results, cell co-culture assays in vitro showed that S100P knockdown in lung cancer cells could inhibit the migration and M2 polarization of primary or cell line-derived macrophages." (PMID 34805160, 2021). "Previous studies have shown that SIX3 acts as a suppressor in lung cancer by modulating proliferation and migration-related genes, such as S100P and TGFB3, and the Wnt/β-catenin signaling pathway is involved in SIX3 function in glioma development and vertebrate forebrain development." (PMID 33264103, 2020). "The expression of S100P (HR = 1.4, 95% CI: 1.02–1.93, and p = 0.0340) and S100B (HR = 0.47, 95% CI: 0.24–0.93, and p = 0.025) was modestly associated with OS in patients with grade II and III lung cancer, respectively." (PMID 29607329, 2018). "This study therefore suggests that S100P represents a critical activator of lung cancer metastasis." (PMID 26320193, 2015). "We investigated the possible role of RAGE and integrins on S100P-mediated lung cancer progression." (PMID 26320193, 2015). "We further confirmed the role of S100P overexpression in lung cancer." (PMID 26320193, 2015). "Thus, inhibition of S100P may provide a novel therapeutic target for combating lung cancer metastasis." (PMID 26320193, 2015). "To investigate the clinical relevance of RBMS1 and S100P in lung cancer, we examined the protein levels of RBMS1 and S100P in fresh‐frozen tumor and paired adjacent normal tissues from 7 patients with NSCLC." (PMID 38342601, 2024). "Most importantly, lung cancer patients with high expression of RBMS1 and S100P had a worse prognosis than those with low expression of RBMS1 and S100P." (PMID 38342601, 2024). "Results indicated a significant downregulation of CX3CL1, MS4A15, and GSTA1 in lung cancer cells, while EPS8L3, G6PD, KRT6A, and S100P were notably upregulated, in line with the bioinformatics analysis findings." (PMID 37315289, 2023). "In lung cancer tissues, HGF and PTX3 expression was downregulated and S100P expression was upregulated." (PMID 34745947, 2021). "Ectopic expression of S100P increases migration, invasion and EMT in less invasive CL1-0 lung cancer cells." (PMID 26320193, 2015). "However, the exact role of S100P in the invasive capacity of human lung cancer remains unknown." (PMID 26320193, 2015). "S100P in AD cells and CDH1 in AD and SQ cells were identified as candidate markers of these lung cancer subtypes based on their upregulation and the results of PCA analysis." (PMID 20142997, 2010). "S100P, significantly upregulated in early-stage LUAD, promotes cancer progression by activating the PI3K/AKT pathway and interacts with interferon β (IFN-beta), indicating its potential role in lung cancer progression." (PMID 40433361, 2025). "However, the exact mechanism how SIX3 and TRIM27 regulate S100P in lung cancer is not known, and thus, warrants further investigation." (PMID 33264103, 2020). "Interestingly, the mRNA level of S100P was not affected by RBMS1 in both the stably RBMS1‐depleted lung cancer cells and in those with RBMS1 transient knock‐down using siRNA, indicating that RBMS1 might regulate the expression of S100P at the post‐RNA level, including translation." (PMID 38342601, 2024). "However, the mRNA level of S100P was not affected by YTHDF1, as judged by RT‐qPCR in the stably YTHDF1‐depleted H460 and A549 lung cancer cells." (PMID 38342601, 2024). "Restoration of SIX3 in lung cancer cells lacking endogenous SIX3 suppressed cell proliferation and migration, and downregulated a number of genes involved in proliferation and metastasis such as S100P, TGFB3, GINS3 and BAG1." (PMID 23977152, 2013).
colon carcinoma (24 papers, 2010 to 2025). "The interaction of RAGE with S100P stimulates major signaling pathways, including ERK1/2, NF-κB, and JAK/STAT, which increased S100P levels in colon cancers linked to metastasis." (PMID 36613714, 2022). "Expression of SOX9 and S100P is strongly correlated in primary colon cancer tissues and is associated with adverse prognosis." (PMID 26009899, 2015). "The clinical sample results expanded our findings in model systems showing that SOX9 and S100P are co-expressed and associated with metastasis and invasion, thereby influencing prognosis in colon cancer." (PMID 26009899, 2015). "The aberrant expression of S100P has been found in various types of cancer, including breast, prostate, pancreatic, lung and colon cancer, and its overexpression is putatively associated with drug resistance, metastasis and a poor clinical outcome." (PMID 25585623, 2015). "Similarly, studies on the downregulation of S100P in colon cancer cell line 8307 suggest that S100P is associated with oxaliplatin sensitivity in the drug-resistant cells." (PMID 33042844, 2020). "Together, these findings led us to hypothesize that SOX9 may directly or indirectly regulate S100P and may be associated with aggressive phenotypes of colon cancer." (PMID 26009899, 2015). "In colon cancer models, S100P knockdown reduces both migration and liver metastasis, highlighting its role in cancer dissemination." (PMID 41404073, 2025). "In colon cancer models, lentivirus-mediated knockdown of S100P significantly reduced tumor proliferation and metastasis, suggesting an oncogenic role." (PMID 41404073, 2025). "Previous experiments have shown that cromolyn can suppress tumor growth signals such as BCL-2 and s100P in the animal model of colon cancer induced by dimethylhydrazine." (PMID 38647571, 2024). "In vitro studies show that S100P is expressed in human colon cancer and stimulates cell growth, cell relocation, ERK phosphorylation, and NF-κB activation; these activities were mediated through RAGE." (PMID 36613714, 2022). "Specifically, the miR-155 level in colon cancer cells was not only upregulated by enforced S100P expression but depended on the receptor of advanced glycation end products (RAGE)." (PMID 35434143, 2022). "Knockdown of SOX9 expression results in reduced invasiveness and metastasis of colon cancer cells and inhibits the tumor growth and peritoneal metastasis in nude mice by inhibiting the S100P/RAGE/ERK/EMT signaling pathway." (PMID 33520987, 2020). "In contrast, suppression of S100P inhibited colon cancer metastasis and growth, although ameliorated mice survival." (PMID 33117687, 2020). "SOX9, S100P transcription factor, increased S100P expression promote metastasis and invasion and result in low survival in colon cancer patients." (PMID 33117687, 2020). "The protein, S100P, is a calcium-binding protein, which is an established marker of inflammation and correlated with both sporadic colon cancer and ulcerative colitis." (PMID 29983891, 2018). "Knockdown of SOX9 expression decreased S100P expression, resulting in the reduced invasiveness and metastasis of colon cancer cells by inhibiting EMT shift." (PMID 26755651, 2016). "Knockdown of S100P in SOX9-overexpressing colon cancer cells dramatically suppressed metastasis and invasion both in vitro and in mice." (PMID 26009899, 2015). "This study contributes to our understanding of the molecular mechanism by which S100P overexpression in colon cancer promotes tumor progression." (PMID 26009899, 2015). "We also detected SOX9 and S100P expression in a tissue microarray with 90 colon cancer cases to provide their clinical relevance." (PMID 26009899, 2015). "By constructing a SOX9-overexpressing and S100P knockdown colon cancer cell line, we confirmed that knockdown of S100P expression can dramatically decrease SOX9-mediated migration and invasion abilities." (PMID 26009899, 2015).
colon carcinoma (continued). "We then utilized the lentivirus expressing S100P-specific siRNA to knockdown S100P expression in HCT116-SOX9(+) cells, thus establishing a SOX9-overexpressing and S100P knockdown colon cancer cell line (HCT116-SOX9(+)/S100P(−))." (PMID 26009899, 2015). "To explore the expression patterns of SOX9 and S100P in colon cancer, we measured the expression levels of SOX9 and S100P in colon cancer tissues by Q-PCR and Western blot analyses." (PMID 26009899, 2015). "SOX9, as a transcription factor of S100P, up-regulates the transcription activity of S100P and promotes metastasis, invasion and poor survival of colon cancer by regulating S100P expression." (PMID 26009899, 2015). "A similar study of S100P knockdown in colon cancer cells also exhibited proliferation rates lower in the knockdown cells when compared to colon cancer cells expressing S100P." (PMID 24821384, 2014). "S100P, another member of the S100 family, has also been related to doxorubicin resistance in colon cancer." (PMID 20515499, 2010). "Others have noted increased expression of S100P in colitis, adenomas and sporadic colon cancer." (PMID 29983891, 2018). "There was a strong correlation between SOX9 and S100P expression in colon carcinomas." (PMID 26009899, 2015). "In conclusion, we demonstrated that SOX9 and S100P are both overexpressed in colon cancer." (PMID 26009899, 2015). "Overall, these results were consistent with our hypothesis that SOX9 induction of S100P overexpression in colon cancer cells stimulates cell migration and invasion through activation of the classical EMT signaling pathway." (PMID 26009899, 2015). "Overexpression of SOX9 (P = 0.038) and S100P (P < 0.001) mRNA was observed in colon cancer." (PMID 26009899, 2015). "The results showed that the expression of SOX9 and S100P in colon cancer had a high concordance." (PMID 26009899, 2015). "Western blot analysis showed that SOX9 and S100P proteins were both up-regulated in colon cancer." (PMID 26009899, 2015). "Q-PCR analysis revealed an average 3.5-fold overexpression of S100P in colon cancer." (PMID 26009899, 2015). "Knockdown of SOX9 expression down-regulated S100P expression, resulting in reduced invasiveness and metastasis of colon cancer cells by inhibiting the activation of receptor for advanced glycation end products (RAGE)/ERK signaling and epithelial-mesenchymal transition (EMT)." (PMID 26009899, 2015). "Moreover, the linear regression between SOX9 and S100P expression was pronounced in colon cancer TMA analysis." (PMID 26009899, 2015). "In line with this hypothesis, we demonstrated that overexpression of SOX9 induces the expression of S100P in both a colon cancer cell line and human samples, leading to increased cell invasiveness and metastasis as well as activation of epithelial-mesenchymal transition (EMT)." (PMID 26009899, 2015). "S100P promotes EMT, migration and invasion of colon cancer cells by up-regulating S100A4 through AKT activation." (PMID 33842379, 2021). "It has been confirmed that elevated expression of S100P and then interaction with RAGE induce metastases, cell proliferation, and tumor invasion, like in colon cancer." (PMID 33117687, 2020). "As a transcription factor of S100P, SOX9 binds to and activates S100P promoter, and induces invasiveness and metastasis of colon cancer cells." (PMID 26755651, 2016). "MAPK1 phosphorylation was involved in S100p-induced proliferation and metastasis, as well as EMT in colon cancer." (PMID 26928402, 2016). "To demonstrate that S100P is induced as a result of SOX9 overexpression in colon cancer, we performed EMSA and quantitative ChIP assays, and we found that SOX9 protein binds to the potential binding site in the S100P promoter (AAACAAAAG)." (PMID 26009899, 2015). "To explore the clinical relevance of SOX9 regulation of S100P expression in colon cancer, we performed IHC analysis of the tissue microarray (TMA) containing 90 pathologically annotated cases of colon cancer." (PMID 26009899, 2015).
colon carcinoma (continued). "More importantly, S100P was found to be critical for SOX9-mediated metastasis and invasion in colon cancer." (PMID 26009899, 2015). "Among many candidate genes we screened, S100P expression was selectively up-regulated by SOX9 in both colon cancer cell lines and human colon cancer samples." (PMID 26009899, 2015). "After calculating the regression coefficient between the expression scores of SOX9 and S100P, we found that there was a significant linear regression between SOX9 and S100P (R2 = 0.782, P < 0.001) in primary colon cancer." (PMID 26009899, 2015). "More importantly, S100P plays a pivotal role in SOX9-induced metastasis and invasion of colon cancer." (PMID 26009899, 2015). "Exogenous S100P stimulates cell proliferation, migration, invasion, and activates MAP kinase and NF-κB pathways via RAGE ligation in pancreatic and colon cancer cell lines." (PMID 21559403, 2011). "S100P, a RAGE ligand, has been found in prostate, pancreatic, lung, breast, and colon cancers." (PMID 36613714, 2022). "S100P regulates the calcium signal transduction pathway to mediate cytoskeletal interactions and is induced by the prostaglandin E2 (PGE2)/EP4) receptor signalling pathway in colon cancer cells." (PMID 31069013, 2019). "Because SOX9 promotes cell migration and invasion, we investigated whether S100P mediates the effect of SOX9 on cell migration and invasion in colon cancer cells." (PMID 26009899, 2015). "Hence, the inhibition of S100P, RAGE, or miR-155 could suppress colon cancer growth and metastasis." (PMID 35434143, 2022).
colorectal cancer (20 papers, 2012 to 2024). A primary or metastatic malignant neoplasm that affects the colon or rectum. "We observed increased levels of S100P, which encodes a member of the S100 calcium‐binding proteins, and whose upregulation has been linked to increased metastatic potential and decreased chemosensitivity in colorectal cancer." (PMID 33817986, 2021). "Evidence for S100P being a viable anticancer target is also provided by an aptamer approach in colorectal cancer with high affinity to and selectivity for S100P protein." (PMID 36985425, 2023). "Recent studies have reported that S100P is a new target gene of MACC1 that drives colorectal cancer metastasis and serves as a prognostic biomarker." (PMID 36276281, 2022). "S100P is overexpressed in colorectal cancer tissues and participates in regulating cell invasion and metastasis by binding to the SLC2A5 promoter, thereby reducing its methylation and activating its transcription." (PMID 36187124, 2022). "The S100P protein has been suggested as a potential novel prognostic biomarker of colorectal cancer." (PMID 33466593, 2021). "S100P is present in breast, gastric, ovarian, pancreatic, and prostate cancer and colorectal carcinoma, and the S100P-RAGE interaction activates ERK and NF-κB signaling pathways in NIH3T3 cells." (PMID 34199060, 2021). "In line with this, it has been shown that treatment of colorectal cancer cell lines with S100P increased proliferation and cell migration." (PMID 33117687, 2020). "We previously reported a novel positive feedback loop between thioredoxin‐1 (Trx‐1) and S100P, which promotes the invasion and metastasis of colorectal cancer (CRC)." (PMID 29383839, 2018). "S100P is a part of the calciosome, which is the set of players regulating signaling mediated by calcium, and more specifically, it has been shown to promote the progression of prostate cancer and metastasis occurrence in colorectal cancer." (PMID 37576552, 2023). "S100P was known to promote EMT in colorectal cancer cells by activating the AKT pathway." (PMID 33842379, 2021). "S100P stimulates growth and promotes the invasion and metastasis of colorectal cancer." (PMID 33466593, 2021). "Indeed, evidence has indicated S100P is among three signature genes that induce liver metastasis in a mouse model of colorectal cancer." (PMID 33117687, 2020). "Besides S100A4 and S100P, we confirmed that the expression of S100A11 is enhanced in colorectal cancer, so the high expression of S100A11 in colorectal cancer leads us to a prediction of the cancer progression state." (PMID 38842658, 2024). "S100P is over-expressed in colorectal cancer but not in SW480 cells." (PMID 29534068, 2018).
prostate carcinoma (17 papers, 2008 to 2023). A carcinoma that arises from epithelial cells of the prostate gland. "Since S100P is associated with prostate cancer progression, the interaction of melittin and S100P may be of special interest for the anticancer effect of melittin against prostate cancer." (PMID 34067049, 2021). "Moreover, NBPF1 induction decreased the expression of S100P, the expression of which is associated with drug resistance, metastasis, and poor clinical outcome in many different cancers such as colon, breast and prostate cancer." (PMID 25958384, 2015). "The EF-hand calcium-binding protein S100P was identified as the most overexpressed protein in xenograft models among hormone-refractory vs. primary untreated strains of CWR22 prostate cancer cells." (PMID 29921791, 2018). "In pancreatic and prostate cancer, the hypomethylation in 5′CpG islands of the S100P gene promoter region has been shown to correlate significantly with S100P mRNA expression." (PMID 25585623, 2015). "Overexpression studies of S100P in prostate cancer reported anchorage independent growth in soft agar." (PMID 24821384, 2014). "A lower frequency is found in prostate cancer, in which S100p is retrieved hypomethylated in 50% of samples." (PMID 23873296, 2013). "Studies on prostate cancer have indicated that S100P expression is regulated by androgens and interleukin-6." (PMID 18282279, 2008). "S100P protein expression was also studied in a series of tumors, consisting of 74 ovarian, 11 pancreatic, 56 gastric, 57 colorectal, 89 breast and 193 prostate carcinomas using a novel anti-S100P monoclonal antibody." (PMID 18282279, 2008). "Also, overexpression of S100P in PC3 prostate cancer cells promotes anchorage-independent growth in soft agar." (PMID 25958384, 2015). "Additionally, S100P is regulated by androgen, and high S100P promotes prostate cancer progression." (PMID 31303963, 2019). "The expression of S100P in the colon is mediated by prostaglandin E2 (PGE2)–prostaglandin E receptor 4 (PTGER4) signaling, in prostate cancer by IL-6, and in breast and cervical by glucocorticoids." (PMID 33005177, 2020). "Data in this paper shows that decreasing LMTK2 expression in prostate cancer cells deprived of androgen results in significantly higher levels of FKBP51 protein as well as increased mRNA levels of AR-dependent genes (KLK2, S100P, TMPRS22 and PSA)." (PMID 26008968, 2015).